MRM3 (mitochondrial rRNA methyltransferase 3)
Description:
S-adenosyl-L-methionine-dependent 2'-O-ribose methyltransferase that catalyzes the formation of 2'-O-methylguanosine at position 1370 (Gm1370) in the 16S mitochondrial large subunit ribosomal RNA (mtLSU rRNA), a conserved modification in the peptidyl transferase domain of the mtLSU rRNA. Also required for formation of 2'-O-methyluridine at position 1369 (Um1369) mediated by MRM2.
Synonyms: RNMTL1; HC90; FLJ10581; RMTL1
Tractability: Small molecule: a structure with a bound ligand is known. PROTAC: ubiquitination databases record sites on it.
Gene: Protein-coding gene on chromosome 17 (782,345 to 792,509, forward strand). Ensembl gene ENSG00000171861.
Subcellular location: Mitochondrion
Subcellular location (Human Protein Atlas): Mitochondria
Pathways (Reactome):
Metabolism of RNA: rRNA modification in the mitochondrion
Gene Ontology:
Molecular function: identical protein binding; protein binding; RNA binding; rRNA (guanosine-2'-O-)-methyltransferase activity; methyltransferase activity; RNA 2'-O-methyltransferase activity; RNA methyltransferase activity; S-adenosylmethionine-dependent methyltransferase activity
Biological process: mitochondrial large ribosomal subunit assembly; rRNA processing; rRNA 2'-O-methylation; RNA processing
Cellular component: mitochondrial matrix; mitochondrion; cytoplasm
Genetic constraint (gnomAD): Loss-of-function variants: 34 observed, 39.1 expected, observed/expected ratio (o/e) 0.87, 90% interval 0.66 to 1.16. The upper end of that interval is the gene's LOEUF score, 1.16, which puts it in group 5 of 6, group 1 being the genes least tolerant of losing a copy. Missense variants: 578 observed, 570.74 expected, observed/expected ratio (o/e) 1.01, 90% interval 0.94 to 1.09. Synonymous variants: 225 observed, 234.5 expected, observed/expected ratio (o/e) 0.96, 90% interval 0.86 to 1.07.
Homologues: Orthologues: chimpanzee MRM3 (99% identical), macaque MRM3 (94% identical), guinea pig MRM3 (85% identical), dog MRM3 (85% identical), pig MRM3 (83% identical), rat Mrm3 (82% identical), mouse Mrm3 (81% identical), rabbit MRM3 (79% identical), tropical clawed frog mrm3 (54% identical), Caenorhabditis elegans T14B4.1 (19% identical). Paralogues in human: TARBP1 (19% identical), MRM1 (15% identical).
Diseases named in the same sentence as MRM3 in open-access papers:
MRM3 is named in the same sentence as 6 diseases in open-access papers, as found by Europe PMC text mining. Sharing a sentence is not in itself a finding about the gene and the disease. The quoted sentences say what the papers report.
glioma (2 papers, 2021 to 2024). A benign or malignant brain and spinal cord tumor that arises from glial cells (astrocytes, oligodendrocytes, ependymal cells). "Moreover, we observed protein expression of MRM1, MRM3, TRMT2B, and NSUN4 to be significantly different between low- and high-grade gliomas, whereas other regulators could not be obtained due to lack of data." (PMID 34566979, 2021).
cerebral aneurysms (1 paper, 2024). "Overall, our findings suggest that CCDC90B, tRNA PusA, and MRM3 may be common risk factors for cerebral aneurysms (ruptured and unruptured), while AIF1 and NAGS are specifically associated with an increased risk of aSAH, unrelated to uIA." (PMID 39087007, 2024). "Dysfunction of OXPHOS function is associated with apoptosis, the mechanism may involve MRM3 influencing cell apoptosis through mitochondrial oxidative phosphorylation, thereby affecting the development of cerebral aneurysms." (PMID 39087007, 2024). "The results suggest that CCDC90B, tRNA PusA, and MRM3 may be common risk factors for cerebral aneurysms (ruptured and unruptured), while AIF1 and NAGS are specifically associated with an increased risk of aSAH, unrelated to uIA." (PMID 39087007, 2024).
cancer (1 paper, 2023). A tumor composed of atypical neoplastic, often pleomorphic cells that invade other tissues. "Similarly, some progressors (CHMP4B, CSTF1, and LSM14B) and suppressors RBPs (ATP5F1A, GTF2E2, RTF1, ELAC2, LRRC47, and MRM3) have never been associated with COAD or READ, but present oncogenic properties in other cancer types." (PMID 37384253, 2023).
MRM3 also shares sentences with these, for which no sentence is quoted: breast ductal carcinoma (1 paper); prostate carcinoma (1); tumor (1).